ABCA1 (ATP binding cassette subfamily A member 1)
Diseases named in the same sentence as ABCA1 in open-access papers (continued):
Sharing a sentence is not in itself a finding about the gene and the disease.
dyslipidemia (continued). "Polymorphisms of rs4149339, rs4743763 and rs2472386 in ABCA1 and three lifestyle factors (physical activity, fried food intake, and dessert intake) were associated with CAD in people with dyslipidemia in southern China." (PMID 30836684, 2019). "In the current study, we explored associations of APOA1, ABCA1, and LCAT genes with dyslipidemia and focused on gene polymorphisms involved in the RCT system." (PMID 29758034, 2018). "Our findings suggested that the interaction among APOA1, ABCA1, LCAT conferred the genetic susceptibility to dyslipidemia in Xinjiang Rural Area." (PMID 29758034, 2018). "In this modern environment, the ABCA1, APOE (ε2 and ε4) and LCT polymorphisms have been associated with obesity, dyslipidemias, type 2 diabetes and other metabolic alterations." (PMID 29125573, 2017). "We compared HAE and ABCA1-mediated cholesterol efflux capacity in subjects diagnosed with metabolic syndrome and a corresponding healthy control group." (PMID 24015188, 2013). "HAE was impaired in metabolic syndrome patients similar to ABCA1-mediated cholesterol efflux (Pearson's r = 0.43; P = 0.02)." (PMID 24015188, 2013). "Recently, a role for the CD36 scavenger receptor as well as for the ATP-binding cassette transporter A1 (ABCA1) in the genesis of HIV-related dyslipidemia has been propsed." (PMID 22558273, 2012). "It would be of interest to evaluate whether patients with metabolic syndrome or diabetes who show low expression of Abca1/Abcg1 in monocytes due to hyperglycemia also show low Abca1/Abcg1 expression in bladder SMCs." (PMID 39931819, 2025). "In the ApoE−/− mice treated with an HFD and LPS, RES ameliorated dyslipidemia and atherosclerotic lesions in the aortas and coronary arteries, upregulated the expression of ABCA1 in the aortas, and reduced the levels of costimulatory molecules and inflammatory cytokines in spleens and serum." (PMID 39759494, 2024). "Both the ABCA1 Ct values and fold change were found to be statistically significant (p = < 0.05) among the two groups of only diabetics and diabetics with dyslipidemia by comparing the means via independent t test." (PMID 37821518, 2023). "Collectively, the loss of function of ABCA1 leads to dyslipidemia, and currently, there are no efficient drugs targeted to lower TC and HDL-C levels." (PMID 35743794, 2022). "Moreover, associations between DNp and DN/DNp and ABCA1 and NOS3 SNPs were common due to their influence on dyslipidemia and hypertension, which ultimately reduces kidney function." (PMID 35069435, 2021). "Based on these and other data, ABCA1 was proposed as a candidate gene for metabolic syndrome." (PMID 34201488, 2021). "Based on previous observations, we hypothesized that dyslipidemia is jointly caused by the APOA1, ABCA1, and LCAT genes and their interactions with environmental factors." (PMID 29758034, 2018). "However, comprehensive studies with large sample sizes and involving different ethnic populations are required to understand the contribution of the ABCA1 genotype to dyslipidemia and its further influence on cognition in T2DM." (PMID 28824418, 2017). "Recently, it has been shown that polymorphisms in ABCA1 and ABCC8 may be associated with metabolic syndrome." (PMID 26788366, 2015). "Accumulating evidence suggests that dysregulation of ABCA1 may mediate dyslipidemia." (PMID 35743794, 2022). "Studies suggest that ATP-binding cassette transporter A1 (ABCA1 C69T) polymorphism is associated with a decreased incidence of type 2 diabetes mellitus (T2DM) and that there is an association between ABCA1 C69T polymorphism and the risk of dyslipidemia in diabetic individuals." (PMID 36553543, 2022).
dyslipidemia (continued). "Therefore, SREBP1c, FAS, PPARα, LXR, CYP7A1, and ABCA1 mRNA expression levels were evaluated in our study to investigate whether green tea leaf powder could influence the dyslipidemia in HFD-fed mice." (PMID 33281537, 2020). "Therefore, to explore gene-gene and gene-environment interactions underlying dyslipidemia, we investigated five (rs670, rs1800976, rs4149313, rs2292318, rs1109166) single nucleotide polymorphisms (SNPs) located in APOA1, ABCA1, and LCAT based on a model RCT pathway." (PMID 29758034, 2018). "Therefore, ABCA1 appears to be a promising therapeutic target for metabolic syndrome." (PMID 27139226, 2016). "Deficit of both ABCA1 and ABCG1 leads to more significant β-cell function abnormalities than either transporter alone, leading to dyslipidemia and diabetes." (PMID 38532421, 2024). "We aimed to explore the association of single nucleotide polymorphisms (SNPs) in the ATP-binding cassette subfamily A member 1 (ABCA1) and lifestyle factors with coronary artery disease (CAD) in dyslipidemia." (PMID 30836684, 2019). "This study was aimed at evaluating and comparing ABCA1 and ABCG1 genes expression in metabolic syndrome patients and healthy individuals." (PMID 26788366, 2015). "In subjects with metabolic syndrome, HAE and ABCA1-mediated efflux were reduced to a similar degree compared to the control group, and there were strong correlations between cholesterol efflux capacity and HAE." (PMID 24015188, 2013). "However, the potential impacts of MTX induced HY27 and ABCA1 expressions might be compensated by relatively normal to low cholesterol intake in these subjects; and that the potential atheroprotective effects from HY27 and ABCA1 may only be present in those persons with pre-existing dyslipidemia." (PMID 21232092, 2011). "ABCA1 is involved in the progression of various cancers and pathological biological processes, including dyslipidemia, neurological disorders, glaucoma, and diabetes However, the effect of ABCA1 on the heterogeneous TME of GAC has not been fully elucidated." (PMID 37874419, 2023). "Thus, dyslipidemia is influenced by APOA1, ABCA1, LCAT, environmental factors, and their interactions." (PMID 29758034, 2018). "Soluble Nef can also mediate dyslipidemias in SIV-infected rhesus macaques (infection for 2 months following 6 months of a proatherogenic diet of high cholesterol and saturated fats) by decreasing liver ABCA1 expression and impairing reverse cholesterol transport." (PMID 27117277, 2016). "The non-CHD indications of clinically used drugs included dyslipidemias (PPARA), type 2 diabetes (PPARG and NDUFA13), autoimmune diseases (TNF), neoplasms (RAF1 and PSMA5), circulatory disorders (ABCA1, PLG, ITGB3, and F2), and alcohol-dependency (ALDH2)." (PMID 34675202, 2021). "Moreover, there is evidence that AHInon-REM has a stronger relation with dyslipidemia in patients with OSA and in line with this concept, our correlation analysis indicated a stronger correlation of total and ABCA1 CECs with non-REM AHI in comparison to AHIREM." (PMID 36344946, 2022).
Obesity (64 papers, 2008 to 2025). Accumulation of substantial excess body fat. "For the SNP ABCA1 (rs9282541; G>A), the risk allele (A) frequency was similar between the normal-weight group (0.05) and the obesity group (0.08)." (PMID 39408369, 2024). "Abca1 and Plin2 are marker genes for metabolically activated macrophages in response to obesity-associated cues." (PMID 34608215, 2021). "There are two single nucleotide polymorphisms (SNPs) of the ABCA1 gene, R219K and I883M, that have been found to have a close relationship with susceptibility to obesity." (PMID 32774439, 2020). "The preceding observations indicate that ABCA1 gene polymorphisms and overweight/obesity are correlated." (PMID 26891315, 2016). "We also found that rs2515602, rs2230806 and rs4149313 in ABCA1 gene variants were significantly related to risk of overweight/obesity." (PMID 26891315, 2016). "In addition, it has been reported that ABCA1 mRNA expression is influenced by risk factors such as smoking, age, diet and obesity." (PMID 37988669, 2023). "Visual representations of output gene patterns by dataset are presented in S5, S6, S7 and S8 Figs. Graphs illustrated again coherent gene-gene interactions within the context of obesity research (e.g. the gene association patterns governed by the locus Abca1 reported in the dataset GSE70529)." (PMID 32275707, 2020). "Obesity is associated with reduced expression of ABCA1 in visceral adipose tissues." (PMID 32774439, 2020). "Previous studies found that ABCA1 R230C/C230C genotypes were associated with obesity." (PMID 31010439, 2019). "We thus analyzed whether the functional private ABCA1-R230C risk allele might interact with the most replicated obesity risk allele FTO rs9939609." (PMID 28464932, 2017). "Whether ABCA1 gene polymorphisms and overweight/obesity are correlated among Uyghurs should be determined." (PMID 26891315, 2016). "A study shows that the ABCA1 R230C variant was associated with obesity and low HDL-C levels." (PMID 26828509, 2016). "The interactions of ABCA1 gene polymorphisms and obesity on serum HDL-C levels are limited." (PMID 26828509, 2016). "This association may partly result from ABCA1 gene mutations, which can lead to an inflammatory reaction and an increase in the risk of overweight/obesity." (PMID 26891315, 2016). "Finally, our results show that the low HDL-C disease was partly influenced by the interactions of ABCA1 gene polymorphisms and obesity." (PMID 26828509, 2016). "Information about the association of ABCA1 gene haplotype and overweight/obesity is limited." (PMID 26891315, 2016). "Second, although we have discussed the relationship between ABCA1 six SNPs polymorphisms and overweight/obese, the mechanism of ABCA1 gene polymorphism and overweight/obesity remains unclear." (PMID 26891315, 2016). "Thus, obesity or overweight may induce effects directly linked to ABCA1 function that may interact with the ABCA1 polymorphism." (PMID 34975757, 2021). "Recently, results reported by Tobi and colleagues and our group also suggested that adverse fetal environmental conditions might have persistent epigenetic consequences on the ABCA1 epigenetic profile and predispose newborns to develop obesity, diabetes and CVD." (PMID 25093045, 2014). "ABCA1 and ABCG1 promote cholesterol and lipid efflux, mitigating inflammatory effects associated with obesity by maintaining the levels of anti-inflammatory HDL particles." (PMID 40770069, 2025). "LXRα, ABCA1, and ABCG1 were negatively associated with ALT levels, which is related to lipid metabolism and obesity and reflects hepatocellular injury in patients with NAFLD." (PMID 39062791, 2024). "In a cohort of Northwest Mexican adults, single-nucleotide polymorphisms (SNPs) in the ABCA1 gene as well as FTO alpha-ketoglutarate-dependent dioxygenase (FTO), adrenoceptor beta 3 (ADRB3), and PPARG were associated with increased risk of obesity." (PMID 38027204, 2023).
Obesity (continued). "Breast cancer, prostate cancer, and ectopic carcinoma are only a few examples of obesity-related cancers in which ABCA1 has been shown to play a critical role in regulating metabolism." (PMID 37889548, 2023). "Consistent with increased circulating lipids and fatty acids in obesity, a 6-month WD induced increased expression of fatty acid and lipid transporters Cd36, Fabp4, Fabp5 and Abca1 in liver ECs, which was partially restored by the reversion diet." (PMID 36400935, 2022). "Our previous work has reported lower ABCA1 expression levels in visceral adipose tissue of individuals with obesity than controls." (PMID 33865458, 2021). "Syntrophin Beta 2 (SNTB2) suggestes a role in ERK and SR-BI level, and sphingomyelin metabolism in obesity and have been proved to affect the activity of ABCA1 by stabilizing ABCA1 protein, which affect the catabolism of LDL-C level." (PMID 30498476, 2018). "The n-3 PUFA-rich PO and FO high fat diets were found to upregulate the hepatic ABCA1 mRNA expression in the obesity-insulin resistance rats." (PMID 27101976, 2016). "Although we have discussed the interactions of six ABCA1 SNPs and obesity on low HDL-C disease, there are still many unclear environmental and genetic factors and their interactions that remain to be detected." (PMID 26828509, 2016). "In our present study, we detected interactions between six SNPs of the ABCA1 gene and obesity on low HDL-C disease." (PMID 26828509, 2016). "We found that there were interactions shown between rs3890182, rs2275542, rs1800976, and rs4149313 in ABCA1 gene and obesity in patients with low HDL-C." (PMID 26828509, 2016). "ABCA1 expression is reduced in patients with obesity-related metabolic diseases such as hypertension and T2DM, mouse models of insulin resistance and diabetes, and by pro-inflammatory mediators such as TNFα and CRP." (PMID 25045936, 2014). "In 2007, a variant in the ATP binding cassette transporter 1 (ABCA1) gene was found in the Mexican population, implied in the formation of HDL, which was associated with obesity and T2DM in this population." (PMID 24892324, 2013). "ABCA1 gene variant (R230C, rs9282541) apparently exclusive to Native American individuals was also associated with low HDL-C levels, obesity and type 2 diabetes in Mexican Mestizos." (PMID 23039238, 2012). "Further extensive research on gene-diet, gene-physical activity and other gene-environment interactions is required to understand how ABCA1 variants affect the risk of T2DM, obesity and other metabolic traits." (PMID 23152888, 2012). "What is known is that, among individuals of Mexican descent, an association has been described between a variant of gene ABCA1 and lower HDL-C levels, along with a greater risk of developing obesity, MS, and early onset T2DM." (PMID 20529295, 2010). "In conclusion, this is the first time that it has been described that the expression of LXRα, ABCA1, ABCG1, and Ob-Rb in PBMCs was decreased in patients with MO before and after RYGB and was associated with several variables related to obesity, inflammation, and liver function." (PMID 39062791, 2024). "Thus, the efficacy of MSC transplantation for mice with obesity was improved by the ABCA1-dependent effects of melatonin." (PMID 33546749, 2021). "Furthermore, GPS2 has been found to be downregulated in obese and T2DM subjects, providing additional evidence for the repression of ABCA1 in obesity and T2DM." (PMID 32774439, 2020). "Thus, the changes in AER appear to capture more of the clinical changes reflecting the status of obesity (changes in BMI) and diabetes (changes in HbA1c) than the ABCA1-independent CEC assay." (PMID 32260470, 2020). "Our study only focused on diabetes and did not evaluate the correlation of the ABCA1 gene polymorphisms and other disease, such as obesity, cerebral apoplexy and coronary artery disease." (PMID 31010439, 2019).
Obesity (continued). "We identified six microRNAs in the circulation, packaged in adipocyte-derived EVs, that target ABCA1 and are significantly associated with cholesterol efflux capacity in the adolescent with and without obesity." (PMID 31331347, 2019). "The ABCA1-R230C variant (rs9282541) is an ancestry-specific polymorphism private to the Americas and has been strongly associated with low HDL-cholesterol (HDL-C), although its association with BMI and obesity is inconsistent." (PMID 28464932, 2017). "In addition, the FO also exhibited stronger beneficial effects than PO in up-regulating hepatic ABCA1 protein expressions in the obesity-insulin resistance rats." (PMID 27101976, 2016). "Pairwise LD between six SNPs in ABCA1 in the normal weight and overweight/obesity." (PMID 26891315, 2016). "Interactions between the ABCA1 genotypes and obesity in patients with low HDL-C." (PMID 26828509, 2016). "For example, the cholesterol transporter ATP-binding cassette transporter A1 (ABCA1) gene variant (R230C, rs9282541) is unique to Native American individuals and has been associated with low high-density lipoprotein cholesterol (HDL-C) levels, obesity and type 2 diabetes in admixed Mexicans." (PMID 38784134, 2024). "The aim of this study was to explore whether interactions between FTO rs9939609 and ABCA1 rs9282541 affect BMI and waist circumference (WC), and could explain previously reported population differences in FTO-obesity and FTO-BMI associations in the Mexican and European populations." (PMID 28464932, 2017). "Therefore, dietary fat-induced down-regulation of Abca1 and up-regulation of Scd1 and Srebf1 might contribute to development of obesity and/or insulin resistance." (PMID 18457598, 2008). "Proteins involved in lipid metabolism including ABCA1, CD36, and PLIN2 were reported to be specifically up-regulated in metabolically active macrophages in obesity." (PMID 40244655, 2025). "In a mouse model of obesity, using UCB-MSCs, we showed that melatonin treatment improved the efficacy of stem cell transplantation therapy, which was abolished following ABCA1 inhibition." (PMID 33546749, 2021). "In addition, recent study evaluated effects of GDM and obesity on the intrauterine metabolic milieu in the fetus, showing exposure to maternal obesity in utero leads to sex-specific changes in miRNA and expression of several target genes, including ABCA1 in human fetal liver." (PMID 34975757, 2021). "ABCA1 and ABCG1 gene expression in subcutaneous and visceral adipose tissue has been shown to be dysregulated in obesity and during metabolic syndrome development." (PMID 34837967, 2021). "Since the ABCA1, ABCA7 and ABCG1 proteins actmainly in the cholesterol metabolism, and cholesterol dysfunction in the adiposetissue could be related to a lipid imbalance in the whole body, geneticpolymorphisms in the corresponding genes could be involved in obesity-associatedmetabolic complications." (PMID 32745159, 2020). "Subcutaneous and visceral adipose tissue biopsies from 22 class III obesity patients were analyzed for FTO and ABCA1 mRNA expression." (PMID 28464932, 2017). "The target genes regulated by PPARα and involved in lipid metabolism and obesity include CD36, LPL, ACC, ABCA1, CYP4a10, CYP4a14, UCP2, ACO and SCD1." (PMID 24705395, 2014). "The interactions of ABCA-1 (SBP and PP), LDL-R (DBP), LIPC (SBP and DBP), and SCARB1 (PP) and overweight/obesity on blood pressure levels were also detected." (PMID 23109900, 2012). "The SNPs of ABCA-1 (SBP and PP), LDL-R (DBP), LIPC (SBP and DBP), and SCARB1 (PP) were shown interactions with overweight/obesity to influence blood pressure levels (p < 0.01–0.001)." (PMID 23109900, 2012). "Likewise, deletion of some metabolic-related genes, such as FAS, Abca1, regulates HFD-induced obesity in mice via interrupting both adipocytes hypertrophy and differentiation." (PMID 40702315, 2025).